OR8U1 (olfactory receptor family 8 subfamily U member 1)
Description:
Odorant receptor.
Tractability: Antibody: UniProt places it where antibodies can reach, with medium confidence; UniProt predicts a signal peptide or a membrane-spanning region; its Gene Ontology location is reachable by antibodies, with medium confidence.
Gene: Protein-coding gene on chromosome 11 (56,375,624 to 56,376,553, forward strand). Ensembl gene ENSG00000172199.
Subcellular location: Cell membrane
Pathways (Reactome):
Sensory Perception: Expression and translocation of olfactory receptors
Gene Ontology:
Molecular function: olfactory receptor activity; G protein-coupled receptor activity
Biological process: G protein-coupled receptor signaling pathway; sensory perception of smell; detection of chemical stimulus involved in sensory perception of smell
Cellular component: plasma membrane; membrane
Genetic constraint (gnomAD): Loss-of-function variants: 3 observed, 4.39 expected, observed/expected ratio (o/e) 0.68, 90% interval 0.31 to 1.63. That is too few expected variants to judge how well the gene tolerates losing a copy. Missense variants: 368 observed, 339.14 expected, observed/expected ratio (o/e) 1.09, 90% interval 1 to 1.18. Synonymous variants: 123 observed, 109.34 expected, observed/expected ratio (o/e) 1.12, 90% interval 0.97 to 1.31.
Homologues: Orthologues: chimpanzee OR8U1 (95% identical), macaque OR8U1 (94% identical), dog OR8U1 (89% identical), mouse Or8u9 (86% identical), rabbit OR8U1 (86% identical), rat Or8u9 (85% identical), guinea pig OR8U1 (73% identical). Paralogues in human: OR8U3 (68% identical), OR5B12 (58% identical), OR8J1 (58% identical), OR8J2 (57% identical), OR8K3 (57% identical), OR8K5 (57% identical), OR8K1 (57% identical), OR8J3 (56% identical), OR5B21 (55% identical), OR5AP2 (55% identical), OR5AR1 (55% identical), OR8D1 (54% identical), and 84 more.
Diseases named in the same sentence as OR8U1 in open-access papers:
OR8U1 is named in the same sentence as 3 diseases in open-access papers, as found by Europe PMC text mining. Sharing a sentence is not in itself a finding about the gene and the disease.
colon cancer (1 paper, 2012).
OR8U1 also shares sentences with these, for which no sentence is quoted: ovarian carcinoma (1 paper); tumor (1).